SOX1-OT (SOX1 overlapping transcript)
Synonyms: uc.357; LINC00403
Gene: Long non-coding RNA gene on chromosome 13 (112,056,845 to 112,110,570, forward strand). Ensembl gene ENSG00000224243.
Diseases named in the same sentence as SOX1-OT in open-access papers:
SOX1-OT is named in the same sentence as 5 diseases in open-access papers, as found by Europe PMC text mining. Sharing a sentence is not in itself a finding about the gene and the disease. The quoted sentences say what the papers report.
cancer (2 papers, 2023 to 2025). A tumor composed of atypical neoplastic, often pleomorphic cells that invade other tissues. "Having in mind that SOX1 has oncogenic activity in GBM and that SOX1 and SOX1OT expressions correlate in some cancer cell lines, it would be interesting to analyze SOX1OT expression in GBM." (PMID 37047365, 2023).
SOX1-OT also shares sentences with these, for which no sentence is quoted: -carcinoid (1 paper); esophageal cancer (1); renal cell carcinoma (1); T-cell chronic lymphocytic leukemia (1).